ALB (albumin)
Diseases named in the same sentence as ALB in open-access papers (continued):
Sharing a sentence is not in itself a finding about the gene and the disease.
sarcopenia (continued). "Among independent prognostic factors discovered herein, sarcopenia and albumin were the only factors that can possibly be manipulated." (PMID 36248997, 2022). "In the multivariate analysis, sarcopenia, albumin, N stage and TNM stage were identified as independent prognostic factors of survival." (PMID 35501704, 2022). "For example, regarding albumin and sodium levels, if albumin or sodium level decreases, sarcopenia chances increase, p < 0.0001." (PMID 34746216, 2021). "Only GNRI was related to leptin change largely due to the main constituents of this index, i.e., albumin and body weight, and due to the better performance in detecting sarcopenia." (PMID 34441040, 2021). "A significant protective effect of PA on sarcopenia was found among the older adults after adjusting for sex, institutionalization, age, BMI, albumin, hemoglobin, HDL-C levels, history of cardiovascular disease, education level and alcohol drinking." (PMID 34075104, 2021). "The obtained results indicated that there were significant differences in age, cardiac disease, sarcopenia, BMI, serum albumin, and hemoglobin between the two groups (P < 0.05)." (PMID 34912895, 2021). "A previous study compared the sarcopenia-associated factors between high-volume HDF and high-flux HD, and showed that patients who underwent high-volume HDF exhibited a trend of lower serum albumin level than those who underwent high-flux HD." (PMID 34336874, 2021). "EpiDat, version 3.1 was used for the meta-analysis; mean differences with the albumin scores disaggregated by sarcopenia were analyzed by the random-effects model." (PMID 34559500, 2021). "As cancer sarcopenia results from chronic systemic inflammation, the combination of BMI, serum albumin, and inflammation markers (NLR) can more accurately assess cancer sarcopenia." (PMID 35198586, 2021). "In elderly populations, low serum albumin concentrations have been correlated with sarcopenia, which is defined as low levels of skeletal muscle mass." (PMID 33397493, 2021). "In terms of protein state, patients with sarcopenia had lower value in total protein, albumin, prealbumin, A/G than the control (P<0.001)." (PMID 34956096, 2021). "The sarcopenia/short‐distance group had significantly greater age, lower BMI, higher prevalence of peripheral vascular disease, lower albumin and haemoglobin levels, and higher total neutrophil count than the non‐sarcopenia/long‐distance group." (PMID 33665984, 2021). "Lower serum albumin level reflects lower muscle mass and sarcopenia and, hence, reduced functional performance." (PMID 33349082, 2021). "In particular, the serum albumin level, compared with total cholesterol, was significantly lower in terms of OR for sarcopenia by 46% with every 1 g/dL increase." (PMID 34531464, 2021). "Particularly, in patients with advanced CKD above stage 3B, serum albumin levels need to be closely monitored, and if these levels are low, it is necessary to exercise more caution and actively evaluate sarcopenia." (PMID 34531464, 2021). "This retrospective study assessed, for the first time, the risk of poor functional outcome after patella fracture surgery in the elderly using a nomogram prediction model that included three variables: age, sarcopenia, and serum albumin level." (PMID 34912895, 2021). "However, loss of acceptable amounts of albumin may reduce the risk of developing sarcopenia." (PMID 34336874, 2021). "Several nutritional markers have been proposed to be associated with cancer prognosis, including albumin, PNI, BMI, sarcopenia, and many other serum markers." (PMID 34831005, 2021). "Sarcopenia should be considered as an important prognostic factor in LC patients as well as Child-Pugh classification and albumin-bilirubin (ALBI) grade, and the evaluation of sarcopenia has become an essential part of daily practice for CLD patients." (PMID 33925660, 2021).
sarcopenia (continued). "The following five variables showed a significant relationship with sarcopenia in the univariate analysis: age, BMI, albumin, IGF-1, and BCAA." (PMID 33050430, 2020). "Infliximab, a TNF-α antibody, increased both muscle volume and strength in CD patients, and moreover, colectomy increased SMI and serum albumin with a decrease in the prevalence of sarcopenia in UC patients." (PMID 32784808, 2020). "Regarding biochemical parameters, the sarcopenia group had significantly lower levels of albumin (p = 0.035), IGF-1 (p < 0.001), and BCAA (p < 0.001) than the non-sarcopenia group." (PMID 33050430, 2020). "In the probable sarcopenia group, the red blood cell count, hemoglobin level, and hematocrit and serum albumin were obviously lower in men, while the serum creatinine level was higher in women than in the control group." (PMID 33204732, 2020). "Patients in the sarcopenia group were older and more likely to have lower BMI, pulmonary function, and albumin and hemoglobin levels than those in the normal and pre-sarcopenia groups (p < 0.001)." (PMID 33066134, 2020). "The association between reduced preoperative metabolic reserve, manifested by sarcopenia, decreased albumin levels, old age and disease burden, and poor outcome, is familiar to surgeons and adhering to strict patient selection remains the main challenge." (PMID 32238149, 2020). "The findings of our subgroup analysis are also supported by a recent study demonstrating that BCAA supplementation improved the survival rate in cirrhotic patients with sarcopenia and a low albumin level (≤3.5 mg/dL)." (PMID 32429077, 2020). "The level of globulin and HDL-C in the sarcopenia group were significantly higher than those in the non-sarcopenia group, whereas the level of albumin and hemoglobin were significantly lower in the sarcopenia group." (PMID 33160322, 2020). "Urinary albumin level, urinary protein level, and decreased eGFR, which are the indices of sarcopenia and renal function, are related to many common factors such as insulin resistance, inflammation, and oxidative stress." (PMID 31828155, 2019). "We aimed to associate three markers of inflammation, erythrocyte sedimentation rate, albumin and white blood cell count, with measures of sarcopenia in geriatric outpatients." (PMID 31455238, 2019). "Sarcopenia was significantly associated with higher CP score, INR, and blood potassium level (P < 0.001, P = 0.037, and P = 0.035, respectively), whereas albumin levels were lower in patients with sarcopenia than in patients without sarcopenia (P = 0.010)." (PMID 31888500, 2019). "The aim of the present paper is to associate ESR, albumin and WBC count as markers of inflammation, with measures of sarcopenia i.e. physical performance, muscle strength and muscle mass in a cohort of geriatric outpatients." (PMID 31455238, 2019). "Branched-chain amino acid supplementation stimulates albumin and protein synthesis in skeletal muscle and has the potential to improve the prognosis of LC patients with sarcopenia." (PMID 31878909, 2019). "The keywords of this period included ‘homecare’, ‘nutrition’, ‘comorbidity’, ‘sarcopenia’, ‘albumin’, and ‘dementia’." (PMID 29672647, 2018). "The degree centralities of the keywords were in the order of ‘home care’ (0.36), ‘nutrition’ (0.30), ‘comorbidity’ (0.26), ‘sarcopenia’ (0.26), and ‘albumin’ (0.23)." (PMID 29672647, 2018). "Usually, changes in body composition precede the reduction of serum albumin and can show the aging of a human, and, on the other hand, are a necessary element for recognizing sarcopenia or frailty syndrome." (PMID 29510548, 2018). "Numerous studies have demonstrated that there are correlations between sarcopenia and patients' basic characteristics, such as age, sex, liver function(serum albumin levels), and BMI values." (PMID 29254263, 2017).
sarcopenia (continued). "Patients in the sarcopenia group had significantly lower albumin levels and a higher rate of preoperative biliary drainage, but other factors, including intraoperative factors, were not significantly different." (PMID 28549466, 2017). "For clinical biochemical indexes, differences in levels of DBP, ALB, and Cr in male subjects and levels of DBP, ALB, Cr, and Hb in female subjects between the sarcopenia and control groups were statistically significant (P < 0.05)." (PMID 28701179, 2017). "Sarcopenia was positively associated with age, ASA score and polypharmacy, and negatively associated with BMI and albumin." (PMID 28902873, 2017). "Sarcopenia was present in 128 patients (68.8%), and sarcopenic patients had significant serum lymphocyte counts and albumin levels (p = 0.002 and 0.041, respectively), and higher NLRs and CRP levels (p = 0.011 and 0.026) than non-sarcopenic patients." (PMID 27537502, 2016). "The evidence-based clinical practice guidelines for liver cirrhosis (LC) from the Japanese Society of Gastroenterology (JSGE)/ JSH published in 2020 reflect three criteria for initiating nutritional therapy: hypoalbuminemia (serum albumin < 3.5 g/dL), Child–Pugh grade B or C, or sarcopenia." (PMID 40273113, 2025). "In addition, sarcopenia, serum albumin <40 g/L, N 2–3 stage, and lower KPS score were independently associated with a poor OS." (PMID 40051963, 2025). "Cross-sectional study evaluated the association between pro-vegetarian dietary pattern and the risk of protein-energy wasting (assessed by low protein intake, low body and muscle mass, low albumin levels) and sarcopenia (low muscle mass, strength and function) in 109 CKD patients." (PMID 40077766, 2025). "The mean albumin was 3.41 ± 0.46 g/dl at 1-month and 3.54 ± 0.36 g/dl at six-month follow-up in the no sarcopenia group and 2.94 ± 0.31 g/dl at one month and 3.17 ± 0.23 g/dl at six-month follow-up in the sarcopenia group." (PMID 40476129, 2025). "In our study, sarcopenia patients exhibited higher rates of complications, including pressure ulcers (P = 0.031), pulmonary infections (P = 0.001), and organ dysfunction (P = 0.024), alongside increased albumin transfusions requirements (P = 0.002)." (PMID 40730978, 2025). "Improving the nutritional status of the older adults can increase the serum albumin content, which may play a certain role in the treatment of sarcopenia in the older adults." (PMID 40969368, 2025). "Also, in patients with sarcopenia, reduced albumin levels and upregulated expression of inflammatory factors further diminish the synthesis of multiple proteins involved in amino acid conservation." (PMID 41280389, 2025). "When both albumin levels are low and sarcopenia is present, a shift toward palliative strategies may be appropriate; conversely, albumin >3.8 g/dL combined with preserved muscle mass supports more aggressive, curative-intent approaches." (PMID 40805233, 2025). "Background/Objectives: Hip fracture patients commonly exhibit impaired nutritional status, including low serum albumin levels related to sarcopenia, which may affect recovery." (PMID 41375751, 2025). "Sarcopenia correlated with hemoglobin, albumin, CRP, and ESR." (PMID 40476129, 2025). "Although the exact relationship between albumin and SO remains unclear, several studies have demonstrated an inverse relationship between serum albumin levels and the occurrence of sarcopenia." (PMID 40860482, 2025). "In men, sarcopenia was associated with higher CRP levels, lower albumin and GNRI scores, and a greater prevalence of vascular complications, whereas in women, it was related to lower waist circumference, albumin levels, and handgrip strength, as well as a higher frequency of retinopathy." (PMID 41393007, 2025). "Addition of biochemical markers, including haemoglobin and albumin, as well assessment of nutritional status and sarcopenia, could be used to augment current models." (PMID 40095157, 2025).
sarcopenia (continued). "A decline in SMI, BMI, and nutritional markers, including albumin, prealbumin, and the PNI, may serve as indicators for assessing the risk of sarcopenia." (PMID 40740773, 2025). "Sarcopenia patients demonstrated lower T-scores, lower BMI, and serum albumin levels." (PMID 41343088, 2025). "Pathophysiologically, factors such as sarcopenia, chronic inflammation, and protein-energy wasting may have contributed to lower albumin levels." (PMID 41295296, 2025). "Sarcopenia correlation with hemoglobin and albumin in both groups at one- and six-month follow-up." (PMID 40476129, 2025). "Therefore, targeted nutritional support addressing both low serum albumin levels and sarcopenia should be warranted in these vulnerable patients." (PMID 41375751, 2025). "These analyses revealed that sarcopenia, age, albumin, creatinine, INR, muscle density, ARDS, hepatic encephalopathy, AKI, MELD score, Child–Turcotte–Pugh (CTP) score and CLIF‐SOFA score were significantly associated with mortality outcomes in patients with ACLF." (PMID 38965993, 2024). "Our study showed that patients with sarcopenia tended to be thin and had low plasma albumin levels." (PMID 38797769, 2024). "Our mediation analyses identified several key metabolic indicators, including metabolically unhealthy status, HbA1c, vitamin D levels, and albumin levels, as significant mediators in the relationship between sarcopenia, sarcopenic obesity, and the incidence of SUI and MUI." (PMID 39469327, 2024). "Therefore, predicting AKI based on sarcopenia using the PLVI has a greater advantage than relying on serum albumin, which is an inaccurate baseline measurement." (PMID 38792928, 2024). "In dialysis patients, myostatin (AUC 0.79) and IL-6 (AUC 0.67) had a high discrimination value for sarcopenia, and we were able to develop a prediction model for sarcopenia, including age, albumin, adiponectin, and myostatin levels, with an AUC of 0.806 (95% CI: 0.721–0.891)." (PMID 39125361, 2024). "Albumin is synthesized by the liver, and it is well known as a muscle-related parameter that is affected by several mechanisms and often examined in the context of sarcopenia at older age." (PMID 39199416, 2024). "In a sensitivity analysis, the model was analyzed with BMI added as an independent variable, albumin instead of nutritionally at-risk, and decreased grip strength and low muscle mass (present vs. absent) instead of sarcopenia, which yielded similar results." (PMID 38999913, 2024). "Lower albumin, sodium, and platelet levels, in addition to high values of CRP, were also linked to higher mortality in all groups, with the greatest impact in the group with both sarcopenia and frailty." (PMID 39795544, 2024). "Univariate analysis revealed a significant reduction in overall survival in patients with a prognostic nutritional index of <45, C-reactive protein-to-albumin ratio of ≥0.047, cancer antigen 19–9 levels of ≥130 U/mL, sarcopenia, lymph node metastasis, and vascular invasion." (PMID 38913646, 2024). "The findings and the formula described in this study, based on a combination of age, albumin, myostatin, and adiponectin levels, could be a starting point for further research on the rapid initial assessment of sarcopenia in dialysis patients." (PMID 39125361, 2024). "Serum albumin is one of the blood biomarkers representing sarcopenia." (PMID 39666645, 2024). "In the univariate logistic regression analysis regarding neutropenia, sarcopenia (OR 4.23, 95% CI 1.41–12.66, p = 0.01) and preoperative albumin level (OR 0.84, 95% CI 0.72–0.97, p = 0.015) also reached statistical significance and were included in the multivariate logistic regression model." (PMID 36814253, 2023). "Additionally, sarcopenia had a consistent predictive value for postoperative pneumonia across gender, age, BMI, smoking, and pre-albumin subgroups." (PMID 37274285, 2023).
sarcopenia (continued). "However, sarcopenia group was characterized by significantly lower albumin levels than the group of undiagnosed sarcopenia." (PMID 37465171, 2023). "In all participants, univariate and multiple logistic regression analysis showed that albumin was associated with low handgrip strength and sarcopenia but not with low SMI and low walking speed." (PMID 36819693, 2023). "Additionally, it has been shown that sarcopenia correlated with lower preoperative albumin levels in pancreatoduodenectomy patients." (PMID 36769619, 2023). "However, laboratory results are inconclusive with respect to serum albumin levels and, thus, improvement of sarcopenia and PEW." (PMID 37608265, 2023). "The cut-off values of albumin were associated with a diagnosis of sarcopenia only in women but not in the men, BMI < 22 and BMI ≥ 22 subclasses." (PMID 36819693, 2023). "In addition, the essential branched-chain amino acids (BCAAs) are involved in albumin synthesis and the maintenance of skeletal muscle mass, and thus, a decrease in BCAAs is also closely related to the development of sarcopenia in chronic liver disease." (PMID 36986091, 2023). "Malnutrition, routinely indicated by decreased in serum albumin and low BMI, is often comorbid with sarcopenia and may accelerate the process of muscle degeneration." (PMID 37371699, 2023). "The potential of albumin and sarcopenia in diagnosing corticosteroid-refractory disease somewhat supports our hypotheses." (PMID 37481662, 2023). "First, to substantiate the internal validity of our findings, it is worth noting that statistical analyses by sarcopenia condition (presence/absence) showed a higher proportion of males as well as older age, and lower levels of albumin, haemoglobin, vitamin D, and BMI in the sarcopenic population." (PMID 37110223, 2023). "Furthermore, albumin was deemed a predictive biomarker for sarcopenia, with an optimal cut-off point of less than 41.3 g/l, sensitivity of 71.7%, and specificity of 66.7%27." (PMID 37363476, 2023). "In addition, the cohort identified as having sarcopenia had a significant decrease in the concentrations of albumin, pre-albumin, and 25(OH)D." (PMID 38026977, 2023). "Furthermore, we found that a higher BMI and predialysis BUN and higher serum albumin, prealbumin, and phosphate levels were sarcopenia-protective factors in our patients receiving hemodialysis." (PMID 37033264, 2023). "The sarcopenia+ groups in men and women showed lower values in BMI, albumin, and GNRI." (PMID 36819693, 2023). "Interestingly, recent research has shown that preoperative sarcopenia and elevated systemic inflammatory markers, such as the modified Glasgow Prognostic Score including both CRP and albumin levels, were associated with a decreased survival." (PMID 37371699, 2023). "Additionally, changes in serum albumin, nutritional parameters and sarcopenia have been studied as predictive preoperative biomarkers to detect high-risk patients before surgery." (PMID 38098074, 2023). "Although the independent association of sarcopenia and albumin with mortality in patients with renal cell carcinoma (RCC) is well known, there have been few studies on the relationship between sarcopenia and albumin status and RCC." (PMID 37371699, 2023). "In addition, it is known that this specific EAA mixture stimulates the synthesis of both muscle (counteracting sarcopenia) and globular (i.e., albumin) proteins, improving both quality of life and prognoses of cancer patients." (PMID 37242170, 2023). "Besides, our statistical analyses also revealed that the older age and lower serum albumin were correlated with sarcopenia." (PMID 35237317, 2022). "In the present study, the univariate and multivariate linear regression analyses on the global health status revealed that the albumin level and the interaction between sarcopenia and the surgical approach were independent contributors to the global health status." (PMID 36551629, 2022).